CRKL (CRK like proto-oncogene, adaptor protein)
Diseases named in the same sentence as CRKL in open-access papers (continued):
Sharing a sentence is not in itself a finding about the gene and the disease.
myeloid leukemia (3 papers, 2017 to 2021). A clonal proliferation of myeloid cells and their precursors in the bone marrow, peripheral blood, and spleen. "Next, we carried out in vivo study to further investigate the biological effects of CrkL silencing in the progression of myelogenous leukemia." (PMID 34114685, 2021). "In the present study, the main objective was to determine the biological function of CrkL on Dox resistance of myelogenous leukemia and to find the molecular mechanism by which it occurs." (PMID 34114685, 2021). "To investigate the role of CrkL in human myelogenous leukemia, we explored the expression of CrkL in myelogenous leukemia cells (K562 and K562/ADR) and PBMC cells by qRT‐PCR analysis." (PMID 34114685, 2021). "We found CrkL was up‐regulated in human myelogenous leukemia cells and CrkL silencing effectively reduced the Dox resistance and increased apoptosis in K562/ADR cells." (PMID 34114685, 2021). "The results showed that CrkL gene was significantly up‐regulated in myelogenous leukemia cells compared with PBMC cell." (PMID 34114685, 2021). "Our findings bring forth new insights into the role of CrkL on Dox resistance to myelogenous leukemia, and further studies are needed to confirm CrkL as a potential therapeutic target for myelogenous leukemia patients with chemoresistance." (PMID 34114685, 2021). "Thus, we concluded that CrkL silencing inhibited the promotion of myelogenous leukemia in vitro and in vivo." (PMID 34114685, 2021). "Together, we indicated that CrkL is up‐regulated in myelogenous leukemia cells and silencing of CrkL could reverse Doxorubicin resistance effectively." (PMID 34114685, 2021). "Finally, in vivo experiments revealed that CrkL silencing acted a tumor‐suppressing role in myelogenous leukemia via regulating PI3K/Akt/MRP1 signaling." (PMID 34114685, 2021). "In vivo experiments revealed that CrkL silencing suppressed tumor growth of K562/ADR through regulating PI3K/AKT/MRP1 signaling.Together, we indicated that CrkL is up‐regulated in myelogenous leukemia cells and silencing of CrkL could reversed Doxorubicin resistance effectively." (PMID 34114685, 2021). "V-Crk Avian Sarcoma Virus CT10 Oncogene Homolog-Like (CRKL) (GeneID:1399) gene is reported to be involved in the progression of myeloid leukemia, whether circCRKL derived from the CRKL gene is involved in the progression of myeloid leukemia remains unclear." (PMID 34617876, 2021).
pancreatic ductal adenocarcinoma (3 papers, 2015 to 2021). An infiltrating adenocarcinoma that arises from the epithelial cells of the pancreas. "The purpose of the present study was to explore the expression and prognostic value of three adaptor proteins: GRB2-associated binding protein 2 (GAB2), CRK-like protein (CRKL) and fibroblast growth factor receptor substrate 2 (FRS2) in pancreatic ductal adenocarcinoma (PDAC)." (PMID 28558797, 2017). "Two earlier studies reported that GAB2 and CRKL were overexpressed in pancreatic ductal adenocarcinoma (PDAC), but they did not investigate the association of GAB2 and CRKL overexpression with the prognosis of PDAC patients." (PMID 28558797, 2017).
clear cell renal cell carcinoma (2 papers, 2023 to 2024). "In clear cell renal cell carcinoma, it was found that a low expression of miR-429, negatively correlated with the overexpression of CRKL, (v-crk sarcoma virus CT10 oncogene homolog (avian)-like) promoted the aggressiveness of cancer cells and advanced the clinical progression of ccRCC patients." (PMID 38002073, 2023).
COVID-19 (2 papers, 2022 to 2024). A disease caused by infection with severe acute respiratory syndrome coronavirus 2. "The proteins overlapping with the enriched “B-cell Receptor Signaling Pathway (WP23),” JUN, HCLS1, PIK3AP1, and CRKL, were all increased in abundance in the COVID-19 spleen tissue, in addition to IL-18R1." (PMID 34710339, 2022). "The expression of both CrkL and fibronectin was decreased in our COVID-19 cohort." (PMID 38760690, 2024).
liposarcoma (2 papers, 2019 to 2025). A usually painless malignant tumor that arises from adipose tissue. "Combined transcriptomic and proteomic investigations revealed that miR-193b can target and inhibit CRK-like proto-oncogene (CRKL) and focal adhesion kinase (FAK) to slow liposarcoma development." (PMID 39736850, 2025). "In liposarcoma, miR-193b was found to suppress CRKL and FAK to induce apoptosis in liposarcoma cells, halting their growth in vitro and in vivo." (PMID 39736850, 2025).
lymphoma (2 papers, 2020 to 2021). A malignant (clonal) proliferation of B- lymphocytes or T- lymphocytes which involves the lymph nodes, bone marrow and/or extranodal sites. "The trafficking studies above suggest that the ability of CrkL KO T cells to clear lymphoma cells while inducing minimal GvHD pathology stems from their ability to migrate efficiently to lymphoid tissues where the tumor resides, but not to GvHD target organs." (PMID 32391120, 2020).
metastatic melanoma (2 papers, 2022). A melanoma that has spread from its primary site to another anatomic site. "We also found that BRAF class 1 mutations (20.3% vs. 5.8%) were more frequent in metastatic melanomas, while SPRED1 inactivation (3.9% vs. 19.8%), SF3B1 mutations (1.6% vs. 9.3%), and amplifications of CRKL (6.3% vs. 17.4%) and MAPK1 (1.6% vs. 11.6%) were more frequent in primary samples." (PMID 35706047, 2022). "Finally, we investigated whether overexpression of LZTR1 or CRKL releases normal human melanocytes from their dependency on growth factors, a common phenotype of metastatic melanoma cells." (PMID 35197475, 2022).
prostate carcinoma (2 papers, 2021 to 2026). A carcinoma that arises from epithelial cells of the prostate gland. "Other highly connected proteins included ACVR2B (13 edges) and CRKL (12 edges), which were linked to most of the miRNA hubs, but currently have limited evidence supporting a specific role in prostate cancer." (PMID 41598250, 2026). "As Runx2 has been implicated in RANKL expression in various cell types, such as prostate cancer cells, vascular smooth muscle cells, and osteoblasts, we further examined whether CrkL-inhibited Tnfsf11 expression is involved in the regulation of Runx2 expression." (PMID 34209812, 2021).
sarcoma (2 papers, 2021 to 2023). A usually aggressive malignant neoplasm of the soft tissue or bone. "The activated FGFRs regulate the following signaling pathways in the cell through adaptor proteins: 1) Rat sarcoma (RAS)-MAPK pathway: fibroblast growth factor receptor substrate 2α (FRS2α) interacts with Crk-like protein (CRKL) and is phosphorylated by FGFRs kinase." (PMID 34721299, 2021). "Finally, in The Cancer Genome Atlas (TCGA), co-amplification of BCL2L13, BID, CRKL and MAPK1 was present in 0.5% of reported samples, being > 2% among sarcomas or lung squamous cell carcinomas." (PMID 37443114, 2023).
Stroke (2 papers, 2016 to 2021). Sudden impairment of blood flow to a part of the brain due to occlusion or rupture of an artery to the brain. "In the present study, an increase in CRKL protein expression was also seen in stroke patients’ platelets in response to platelet activation." (PMID 27336623, 2016).
autism (1 paper, 2023). Persistent deficits in social interaction and communication and interaction as well as a markedly restricted repertoire of activity and interest as well as repetitive patterns of behavior. "Using the method, we were able to identify and explain possible involvement of pathways including the NK cell functions pathway and genes such as CRKL for the development of autism and/or psychosis in 22q11DS patients." (PMID 37872602, 2023).
behavioral (1 paper, 2025). "Among the genes present in this interval, CRKL is an excellent candidate for cardiac and renal defects, according to studies in humans and mice, whereas PI4KA could be a candidate for the neurological/behavioral disorder aspects." (PMID 39858619, 2025).
breast tumor (1 paper, 2019). "The results show significantly higher levels of soluble CrkL in sera from breast tumor patients as compared to healthy donors, suggesting the potential use of CrkL as a soluble biomarker." (PMID 31323992, 2019). "Similar to in vitro studies in breast tumor cells, high expression of CrkL was detected in clinical breast tumor tissue." (PMID 31323992, 2019). "ELISA was used to assess the soluble CrkL in sera collected from 29 breast tumor patients and 10 healthy donors." (PMID 31323992, 2019). "Our data provide further evidence that expression of CrkL in the breast tumors can serve as a potential tissue biomarker." (PMID 31323992, 2019). "When compared to uninvolved tissue, a 12-fold increase in the CrkL staining intensity was detected in the breast tumor biopsies (3.9 ± 1.9 vs. 48.6 ± 22.1 arbitrary units (A.U.)/pixel, respectively)." (PMID 31323992, 2019). "While our data show a link between the stage of the breast tumor and the levels of soluble CrkL in the patients’ sera, further studies will be required to assess the specific triggers of the extracellularly excreted CrkL." (PMID 31323992, 2019). "In total, 85% of the clinical breast tumor biopsies stained positive for CrkL." (PMID 31323992, 2019). "Expression of CrkL was elevated in 85% of breast tumor tissue sections." (PMID 31323992, 2019). "Breast tumor biopsies varied in staining patterns for CrkL expression." (PMID 31323992, 2019).
cervical tumor (1 paper, 2019). "(A) The ASEs change in opposite direction responded to CRKL expression levels in 40 cervical tumor samples and HeLa cells." (PMID 31133010, 2019). "We analyzed the alternative splicing patterns of the 43 CRKL-regulated ASEs which were used for RT-qPCR validation in the RNA-seq data of 40 cervical tumor samples with 20 showing high CRKL expression and 20 showing low." (PMID 31133010, 2019). "We showed that, both in HeLa cells and cervical tumor clinical samples, CRKL regulates the alternative splicing of genes which are critical in tumorigenesis and cancer progression." (PMID 31133010, 2019). "CRKL showed higher expression in 305 cervical tumor samples compared with 3 normal tissue samples." (PMID 31133010, 2019). "We noticed that the expression difference between the CRKL-high and CRKL-low samples was relatively small, this small difference could at least partially explain the relative low correlation of the RASEs between HeLa cells and cervical tumor samples." (PMID 31133010, 2019).
gastric tumor (1 paper, 2016). "By analyzing the mRNA expression of 38 gastric tumor and 31 adjacent normal samples from GSE13911, we found that CRKL is one of the top ranked differential genes that over expressed in tumor specimens compared with normal tissue." (PMID 27846244, 2016).
gestational diabetes mellitus (1 paper, 2025). "As a downstream effector of the CRKL/C3G axis, Rap1 has been implicated in pregnancy complications such as preeclampsia and gestational diabetes mellitus, yet direct studies on RSA remain to be reported." (PMID 40045194, 2025).
influenza (1 paper, 2013). An acute viral infection of the respiratory tract, occurring in isolated cases, in epidemics, or in pandemics; it is caused by serologically different strains of viruses (influenzaviruses) designated A, B, and C, has a 3-day incubation period, and usually lasts for 3 to 10 days. "Based on data from the Influenza Research Database, we analyzed the prevalence of Influenza_A_NS1_SF33 and Influenza_A_NS1_SF30 SF-VTs corresponding to crk/crkL and PKR-binding sites, respectively, for each of the NS1 classes proposed here using the unique sequence database pdb4535." (PMID 23667580, 2013).
invasive ductal breast carcinoma (1 paper, 2019). The most common type of invasive breast carcinoma, accounting for approximately 70% of breast carcinomas. "Similar expression patterns were found in invasive ductal breast carcinoma (IDC), where CrkL TME overexpression in 37% of the IDC breast tissue samples correlated has been found significantly correlate with advanced p-tumor-node-metastasis stage and tumor metastasis." (PMID 31323992, 2019).
laryngeal carcinoma (1 paper, 2020). Carcinoma that arises from the laryngeal epithelium. "Therefore we suggest CRKL as a potential therapeutic target for a subgroup of laryngeal cancer patients with additional copies of CRKL in the tumor cells." (PMID 31913340, 2020).
lentivirus infection (1 paper, 2020). Virus diseases caused by the Lentivirus genus. "The stable transfection with PCDH-EF1-MCS-T2A-Puro-CRKL vector by Lentivirus infection, combined with puromycin screening led to the stable overexpression of CRKL in HepG2, HCCLM3 and HuH7 cells." (PMID 32326970, 2020).
lymph node metastasis (1 paper, 2017). "In addition to poor tumor differentiation, lymph node metastasis, resection margin, and advanced TNM stage, univariate survival analyses revealed that the expression of GAB2, CRKL, FRS2 and the co-expression of GAB2/CRKL/FRS2 were also indicators for poor clinical outcome." (PMID 28558797, 2017).
metastatic disease (1 paper, 2019). "All patients with metastatic disease had significantly elevated concentration of soluble CrkL in the serum with on average three-fold increase from the baseline." (PMID 31323992, 2019).
RASopathy (1 paper, 2021). Developmental syndromes caused by germline mutations (or in rare cases by somatic mosaicism) in genes that alter the Ras subfamily and mitogen-activated protein kinases that control signal transduction. "The most upregulated phosphoproteins from the RASopathy interactome in NS and NSML, except for CRKL, have already been proposed as key players in these syndromes, namely PZR and Fer kinase." (PMID 34229750, 2021).
T-cell leukemia (1 paper, 2021). A malignant disease of the T-lymphocytes in the bone marrow, thymus, and/or blood. "The T-cell leukemia cell line, Jurkat, revealed parallel findings in CrkL mobility with mimicked antigenic stimulation (TCR stimulation) by anti-CD3 monoclonal antibodies (α-CD3), in combination with recombinant human B7.1 (rhB7.1)." (PMID 34417497, 2021).
triple-negative breast carcinoma (1 paper, 2024). An invasive breast carcinoma which is negative for expression of estrogen receptor (ER), progesterone receptor (PR), and human epidermal growth factor receptor 2 (HER2). "This study compared the differential expression levels of the miRNA-200c-3p and the CRKL in triple negative breast cancer tissues and adjacent tissues." (PMID 38717531, 2024).
tumor (57 papers, 2012 to 2025). "While CRKL has been linked to tumor growth as a candidate oncogene in several human malignancies, including lung adenocarcinoma, LZTR1 is generally considered a tumor suppressor." (PMID 35197475, 2022). "CRKL deregulation is associated with various cancers, which is an interesting biomarker for diagnosis, therapy and prognosis of tumours." (PMID 33523562, 2021). "CrkL has been linked to several molecular pathways related to tumor invasiveness in a number of solid tumors." (PMID 31323992, 2019). "These tumours were characterised by increased phosphorylation of several signalling molecules known to associate with erbB2, including Ptpn11, Plcγ1, Cbl and CrkL, as well as its heterodimerisation partner Egfr." (PMID 25200860, 2014). "Dysregulated metabolism of tumour cell provides an acidic microenvironment that facilitates tumour cell migration and invasion, CRKL deregulation associates with metastasis, and we speculate that CRKL may affect the energy metabolism of tumour cells." (PMID 33523562, 2021). "In most of these studies, loss of either Crk or CrkL resulted in decreases in tumor cell migration and invasion, suggesting that tumor cell migration and invasion are highly demanding cellular processes that require both Crk and CrkL to reorganize the cellular cytoskeletal network." (PMID 33801580, 2021). "What cause that CRKL has highest expression in Stage I tumor need to be further explored." (PMID 31133010, 2019). "CRKL (v-crk sarcoma virus CT10 oncogene homologue (avian)-like) play important roles in tumor metastasis, however, the exact role and underlying mechanism of CRKL in HCC is still unknown." (PMID 29403024, 2018). "Higher CRKL expression is associated with poor patient outcome across multiple tumor types." (PMID 26728244, 2016). "However, a mouse model over-expressing CrkL exhibited an increased incidence of hematopoietic and epithelial cancers and a mammary mouse model over-expressing CrkII was associated with altered mammary gland development and accelerated tumor development." (PMID 22569336, 2012). "It would be interesting to tease out the tumor cell migration and invasion that require both p130Cas and Crk/CrkL from the tumor cell migration and invasion that depend on either p130Cas or Crk/CrkL, but not both." (PMID 40362257, 2025). "Taken together, tumor cell migration, a crucial cancer trait, can occur through the formation of the p130Cas-Crk/CrkL complex." (PMID 40362257, 2025). "Inhibitors of the p130Cas-Crk/CrkL axis, once developed, would enable researchers to tease out the tumor cell migration and invasion that require both p130Cas and Crk/CrkL from the tumor cell migration and invasion that depend on either p130Cas or Crk/CrkL." (PMID 40362257, 2025). "Understanding the tumor cell migration and invasion that require both p130Cas and Crk/CrkL is necessary to further evaluate the role of the p130Cas-Crk/CrkL axis in cancer." (PMID 40362257, 2025). "The overexpression of Crk and CrkL in tumor cells triggered a significant tyrosine phosphorylation of scaffolding molecules, like p130Cas and paxillin, through Src family tyrosine kinases." (PMID 40362257, 2025). "Among them, CRKL is directly functional for Rap1 activation, widely expressed in human tissues including placenta and actively involved in regulating tumor cell behavior similar to EVT." (PMID 40045194, 2025). "Mir335 targets CRKL, thereby inhibiting the migration, invasion, and proliferation of tumor cells, arresting the cell cycle at the G0/G1 phase, and promoting apoptosis in GC cells." (PMID 40150719, 2025). "Such inhibitors would be helpful tools in validating the p130Cas-Crk/CrkL as a potential therapeutic target for invasive cancers in which Crk, CrkL, and p130Cas play critical roles in tumor cell migration and invasion." (PMID 40362257, 2025).